REN (renin)
Diseases named in the same sentence as REN in open-access papers (continued):
Sharing a sentence is not in itself a finding about the gene and the disease.
Hypertension (continued). "Crucially, this excess 11-deoxycorticosterone and corticosterone strongly suppresses the renin–angiotensin–aldosterone system, resulting in the characteristic low-renin hypertension and profoundly suppressed aldosterone synthesis." (PMID 41220582, 2025). "In parallel, renal artery stenosis activates the renin–angiotensin–aldosterone system (RAAS), causing refractory hypertension." (PMID 41169618, 2025). "(P)RR can bind and enhance renin activity, as well as fully activating the biologically inactive prorenin, thereby increasing the production of angiotensin II and inducing hypertension." (PMID 40650317, 2025). "Renin-angiotensin system inhibitors (RASIs), such as angiotensin-converting enzyme inhibitors (ACEIs) and angiotensin receptor blockers (ARBs), are widely used for hypertension treatment by affecting the renin-angiotensin-aldosterone system." (PMID 39289938, 2025). "We selected the renin–angiotensin system (RAS) pathway based on both biological relevance to hypertension and significant bioinformatics findings." (PMID 40430466, 2025). "Atherosclerotic dyslipidemias and hypertension lead to the activation of the renin–angiotensin–aldosterone system." (PMID 41007724, 2025). "This isattributed to various neurohumoral and metabolic alterations, such as increasedinsulin resistance, renin–angiotensin–aldosterone system stimulation, andelevated arterial hypertension." (PMID 39867203, 2025). "Clinically relevant comorbidities such as heart failure and hypertension were more frequent in PeAF patients in contrast to PAF patients, including associated medications such as renin-angiotensin-aldosterone system blockers." (PMID 40980715, 2025). "Animal studies have demonstrated that early supplementation with D‐cysteine or L‐cysteine prevented hypertension and kidney injury in spontaneously hypertensive rats exposed to high salt intake by modulating oxidative stress and the renin‐angiotensin system." (PMID 40661804, 2025). "Within the cardiovascular system, prior cancer therapy appears to contribute to hypertension via effects on endothelial function, sympathetic activity, and the renin-angiotensin system." (PMID 40085293, 2025). "ACE2 variants are associated with pregnancy complications, as well as with a number of other diseases characterised by renin-angiotensin system dysfunction, including COVID-19, hypertension and heart failure." (PMID 39920116, 2025). "Hypertension and cardiovascular disease are closely linked to obesity, as the RAS (renin–angiotensin system) has two pathways that produce opposing physiological effects and has multiple locations, such as cardiac, nervous, pancreatic, and adipose tissues." (PMID 40282897, 2025). "A previous study found that normotensives from the general population aldosterone-to-renin ratio (ARR) possess a stronger predictive value for incident hypertension than renin or aldosterone alone." (PMID 41048520, 2025). "Intrarenal renin-angiotensin system activity amplifies these effects, reinforcing the kidney’s role in hypertension progression." (PMID 40762065, 2025). "This accumulation can mediate aldosterone secretion, leading to sodium retention, either through the renin-angiotensin system or directly by enhancing tubular reabsorption, resulting in hypertension." (PMID 40485860, 2025). "Angiotensin II (Ang II) type 1 receptor (AT1R) signaling pathway is a key component of the renin-angiotensin-aldosterone system (RAAS) that is involved in the development of hypertension." (PMID 41035910, 2025). "Sympathetic hyperactivity in CKD initiates and sustains hypertension via multiple pathways, including increased renin secretion, sodium retention, reduced renal blood flow, and systemic vasoconstriction." (PMID 40868205, 2025). "Consistent with this, offspring of HF-fed dams displayed renal upregulation of Olfr78, a receptor that promotes hypertension through renin release." (PMID 41154477, 2025).
Hypertension (continued). "A total of 724 participants (mean age: 56.4 ± 14.3 years, 71% with hypertension) who underwent aldosterone–renin testing and echocardiography were included in the study." (PMID 41574360, 2025). "Angiotensin II (Ang II), a critical component of the renin–angiotensin–aldosterone system, is well-known for its role in vasoconstriction during hypertension." (PMID 40002839, 2025). "Monogenic hypertension studies have also shown that salt-dependency isattributed to abnormalities in renin-angiotensin-aldosterone signaling." (PMID 40927078, 2025). "Our expert panel opinion, therefore, emphasizes screening at every visit and the use of renin–angiotensin system blockers (ACE inhibitors or ARBs) as first-line agents when hypertension coexists with diabetes." (PMID 41299307, 2025). "Mice deficient in 1α-hydroxylase show increased RAAS activity, leading to hypertension and other symptoms due to elevated plasma renin." (PMID 40453223, 2025). "Hypertension can lead to CKD by pathogenic mechanisms including sodium dysregulation and increased sympathetic nervous system and altered renin-angiotensin-aldosterone system activity." (PMID 40685514, 2025). "It is characterized by severe hypertension and hypokalemia due to excessive renin produced from the juxtaglomerular apparatus on the afferent arteriole of the glomerulus." (PMID 40546339, 2025). "The hydroxymethylcarbonyl isostere was incorporated in the design of KRI-1314, a potent renin inhibitor for the treatment of hypertension, as well as in the design of inhibitors of the HIV-1 protease, β-secretase, and HTLV-I protease." (PMID 41011245, 2025). "Sodium and water are retained to support the increased plasma volume through stimulation by the renin–angiotensin–aldosterone system, although peripheral vasodilation in normotensive pregnancies prevents significant hypertension." (PMID 41254799, 2025). "Hypertension and obesity promote pro-inflammatory cytokines that activate the renin-angiotensin-aldosterone system and sympathetic nervous system which result in adverse effects on blood pressure regulation and renal function." (PMID 40014185, 2025). "Persistently suppressed renin and unexplained hypokalemia in the setting of uncontrolled hypertension, even after renal revascularization, should prompt clinicians to revisit the possibility of primary aldosteronism." (PMID 41356982, 2025). "The renin-angiotensin system is crucial for the common complication of hypertension, known as cardiac remodeling." (PMID 40079000, 2025). "The inhibition of renin–angiotensin–aldosterone system (RAAS) activity is one of the key mechanisms in the treatment of arterial hypertension." (PMID 41156232, 2025). "A study reported that exposure to DDT in mice causes sustained increases in systolic blood pressure, potentially through the activation of the renin-angiotensin system, as evidenced by the attenuation of hypertension following ACE inhibitor treatment." (PMID 40190760, 2025). "Leukotrienes have been considered key contributors to hypertension, probably due to their direct regulatory role in the circulatory system or indirectly via the renin-angiotensin system." (PMID 41488008, 2025). "Well-controlled hypertension with medication was observed in 22.4% (17/76) of the participants, and renin-angiotensin system inhibitors were used in 18.4% (14/76)." (PMID 40131973, 2025). "This study aimed to develop a model of chronic Ang II-induced hypertension in Syrian hamsters and investigate sex-specific differences in blood pressure, renal pathology, and components of the renin-angiotensin system (RAS)." (PMID 41184958, 2025). "In cases of JCTs, excessive renin production manifests as unexplained, treatment-refractory hypertension along with electrolyte disturbances and hyperaldosteronism." (PMID 40989803, 2025).
Hypertension (continued). "Experimental studies, for instance, have shown that vitamin D receptor (VDR) knockout mice develop arterial hypertension when compared to control groups, presumably due to heightened plasma renin levels leading to secondary RAAS activation." (PMID 41516172, 2025). "Despite SHRs being a normal-to-low renin and normal-to-low angiotensin/aldosterone model of hypertension, increased RAAS activity, along with elevated levels of angiotensin II, have been observed in HFD-fed animals." (PMID 40559470, 2025). "Obesity is known to contribute to hypertension through mechanisms such as renin-angiotensin-aldosterone system activation, increased sympathetic nervous system activity, and salt retention." (PMID 41315571, 2025). "We postulate that the elevated renin level likely reflected pronounced renin–angiotensin system activation secondary to renal ischemia and severe hypertension." (PMID 40704299, 2025). "The results of our study provide valuable insight in the dose‐dependent relation between renal pressure and renin release, and its adjustments during hypertension." (PMID 40930784, 2025). "Studies have indicated a connection between the activation of the renin–angiotensin system and its central mediator, Ang II, with the prothrombotic condition observed in hypertension." (PMID 39959581, 2025). "Regarding other cardiovascular treatments, above 51% of patients in the LADA-PC study received a renin-angiotensin inhibitor for arterial hypertension, sixty-four percent received lipid-lowering treatment and 14% antiplatelet agents." (PMID 39946340, 2025). "Black patients have a greater likelihood of having a low renin profile and have been shown to have an attenuated response to renin angiotensin inhibitors for hypertension." (PMID 40868074, 2025). "Obesity-induced hypertension is thought to be mediated by various mechanisms, including increased sympathetic nervous system activity, activation of the renin-angiotensin-aldosterone system, and insulin resistance." (PMID 41327728, 2025). "IR is involved in the etiopathogenesis of hypertension by activating the renin-angiotensin-aldosterone (RAS) system and inducing oxidative stress." (PMID 40007810, 2025). "This intervention aims to disrupt the stimulation of the kidney which leads to vasoconstriction, renin secretion, hyperaldosteronism, and sodium retention, resulting in hypertension often resistant to treatment." (PMID 40509714, 2025). "MiR-181 targets genes regulating blood pressure, contributing to hypertension, and miR-663 reduces blood pressure by controlling renin gene expression." (PMID 40565979, 2025). "In retrospect, the initial clues - suppressed renin, even in the context of significant hypertension - aligned more with primary aldosteronism than secondary aldosteronism." (PMID 41356982, 2025). "Lastly, primary hyperaldosteronism should be considered, especially when hypokalemia and metabolic alkalosis are accompanied by hypertension and low plasma renin activity." (PMID 40777730, 2025). "It typically presents with hypertension, polyuria, hypokalemia, and metabolic alkalosis, along with suppressed plasma renin activity and low aldosterone levels, often accompanied by hypernatremia." (PMID 40493279, 2025). "According to its FDA label, there are five mechanisms by which nebivolol treats hypertension: through decreasing heart rate, decreasing myocardial contractility, decreasing outflow, suppressing renin activity, and vasodilation." (PMID 40927301, 2025). "Blood pressure control in the female group with NVAF is complex, influenced by a higher prevalence of hypertension, particularly in the postmenopausal stage, and the influence of the renin-angiotensin-aldosterone system." (PMID 40026935, 2025). "Hypertension vaccines that are currently under development mainly target the renin-Ang system (RAS) component and have been shown to have significant protective effects against hypertension-induced arterial and renal damage." (PMID 40134277, 2025).
Hypertension (continued). "Other contributors to hypertension include endothelial dysfunction, activation of the renin–angiotensin–aldosterone system and heightened activity of the sympathetic nervous system." (PMID 40599628, 2025). "The mechanism of renovascular hypertension (RVH) caused by RAS involves activation of the renin‐angiotensin‐aldosterone (RAA) system, leading to worsening hypertension." (PMID 40909303, 2025). "The development of hypertension in obese individuals has been attributed to several factors, including inflammation, leptin, and activation of the renin-angiotensin and sympathetic nervous systems." (PMID 40567975, 2025). "Insulin resistance, commonly observed in obesity, contributes to the activation of the renin–angiotensin–aldosterone system, leading to sodium retention, hypertension, and further renal stress." (PMID 40150467, 2025). "Vericiguat, an sGC stimulator, caused vasodilatation of the saphenous artery and aortic rings of rabbits and attenuation of hypertension in blood pressure in L-NAME-treated renin-transgenic rats." (PMID 40001929, 2025). "SLE and lupus nephritis likely contribute to the development of hypertension through multiple complex mechanisms including chronic inflammation, oxidative stress, endothelin, renin–angiotensin system, and metabolic derangement in our case." (PMID 39918729, 2025). "The renin-angiotensin-aldosterone system (RAAS) plays a central role in the pathophysiology of hypertension, making it a cornerstone target for therapeutic intervention." (PMID 41409925, 2025). "Data from an adult rat model showed that exposure to dichlorodiphenyltrichloroethane (DDT) during pregnancy induces hyperactivation of the renin-angiotensin system, leading to hypertension and cardiac hypertrophy." (PMID 40190760, 2025). "A sedentary lifestyle and overeating lead to obesity, impaired glucose and lipid metabolism, activation of the renin-angiotensin-aldosterone system, and arterial hypertension contributing to LV hypertrophy." (PMID 40149720, 2025). "Therapy contributes to hypertension due to effects on endothelial function, sympathetic activity, and the renin-angiotensin system, in addition to direct nephrotoxicity." (PMID 40085293, 2025). "Comprehensive studies have shown that ARBs influence the renin–angiotensin system (RAS) by increasing the levels of the ACE2 enzyme more than other hypertension medications." (PMID 41009387, 2025). "Variables such as age, duration of hypertension, aldosterone-to-renin ratio, body mass index, and the presence of target organ damage have been previously reported as significant determinants of clinical success." (PMID 40778273, 2025). "Despite these mixed results, firibastat's novel mechanism of action highlights its potential in addressing hypertension in populations less responsive to conventional therapies, such as those with low renin activity or salt sensitivity." (PMID 40454237, 2025). "This is consistent with what we saw in our 15-year-old female patient incidentally discovered to have hypertension with only occasional headaches and a renin that was 20-fold the upper limit of normal." (PMID 40546339, 2025). "These bioactive peptides have been shown to inhibit the activity of angiotensin converting enzyme (ACE), a component of the renin-angiotensin system that mediates systemic hypertension." (PMID 39013196, 2025). "The manifestations of hypertension, hyperaldosteronism, suppressed renin, elevated urinary aldosterone excretion, sodium overload and potassium overexcretion were highly consistent with the clinical manifestations of PA in humans." (PMID 39946402, 2025). "Angiotensin II (Ang II), the primary bioactive peptide of the renin–angiotensin system, is a well-established contributor to hypertension through its roles in vascular contraction and adverse remodeling, which elevate peripheral resistance." (PMID 41155608, 2025).
Hypertension (continued). "Clinically, this manifests as hypertension (with suppressed renin), hypokalemia, hyperandrogenism, and genital ambiguity." (PMID 41234966, 2025). "The three characteristic signs of PA are an increased aldosterone serum level, a reduced renin serum level, and hypertension." (PMID 39859256, 2025). "The inhibition of the renin–angiotensin–aldosterone system (RAAS) is one of the key mechanisms in the treatment of hypertension." (PMID 41156232, 2025). "Renal injury induced by hypertension is complex, with the core process involving the activation of the renin–angiotensin–aldosterone system (RAAS), along with vascular endothelial dysfunction, oxidative stress, and inflammatory processes." (PMID 40284165, 2025). "The most common mechanism involved in the pathophysiology of hypertension is the renin–angiotensin–aldosterone system (RAAS)." (PMID 40137963, 2025). "This phenomenon can be attributed to the fact that hypertension can induce activation of the renin-angiotensin system (RAS) in the vascular wall through mechanical forces." (PMID 40314886, 2025). "The hypertension and increased renin level are also implicating the hypertrophy signal in 2K1C rats." (PMID 39886537, 2025). "Several mechanisms contribute to the development of hypertension in AoC, including upregulation of the renin–angiotensin system, impaired vasoreactivity, aortic arch geometry abnormalities, baroreflex dysfunction, and abnormal aortic distensibility." (PMID 40260103, 2025). "Additional investigations, such as echocardiogram, tests for renin and aldosterone, cortisol, thyroid function and catecholamines, should be performed once hypertension is confirmed." (PMID 40628975, 2025). "Inappropriate renin secretion, leading to high levels of angiotensin II and aldosterone, facilitates vasoconstriction and impairs urinary sodium excretion, accelerating hypertension and renal dysfunction." (PMID 39349898, 2025). "Though benign, clinically they usually manifest as uncontrolled hypertension with hypokalemia due to the effects of secondary hyperaldosteronism from dysregulation of the Renin‐Angiotensin‐Aldosterone axis." (PMID 39568313, 2025). "Activation of the sympathetic nervous system in animals through oxidative stress generates the activation of the renin-angiotensin-aldosterone system and the subsequent release of catecholamines and hypertension." (PMID 40333700, 2025). "The risk gene AGT, a key component of the renin-angiotensin system (RAS), highlights the intersection of systemic hypertension and neurodegeneration." (PMID 40355913, 2025). "The ACE is a key enzyme involved in the renin-angiotensin-aldosterone system involved in pathophysiology of many diseases such as arterial hypertension, heart failure, and even cancer." (PMID 40893793, 2025). "Our case follows reports of resolution of hypertension in 89% of patients and normalization of renin values in 95% of patients after tumor resection (both complete nephrectomy and partial nephrectomy have been utilized successfully)." (PMID 40546339, 2025). "This manifests as increased plasma renin activity (+230%) and sustained hypertension (systolic blood pressure elevation ≥25 mmHg)." (PMID 41157922, 2025). "Endocan has been scarcely explored in COVID-19, especially regarding its modulation by veno-venous extracorporeal membrane oxygenation (VV-ECMO), hypertension or previous renin–angiotensin–aldosterone system (RAAS) inhibitors treatment." (PMID 39862311, 2025). "We assessed the diagnostic performance of SSIT and OSLT in a group of patients with hypertension and elevated screening aldosterone–renin ratio (ARR)." (PMID 39911522, 2025). "In 1898, Bergman and Tigerstedt1 demonstrated that infusions of renal homogenates, attributed to the presence of the renal hormone renin, elevated blood pressure (BP) in rabbits, there by establishing the foundational role of renal mechanisms in hypertension." (PMID 40762065, 2025).